HMGB1 (high mobility group box 1)
Diseases named in the same sentence as HMGB1 in open-access papers (continued):
Sharing a sentence is not in itself a finding about the gene and the disease.
sarcoma (3 papers, 2021 to 2024). A usually aggressive malignant neoplasm of the soft tissue or bone. "The action of HMGB1 on tumor-associated myeloid cells and their impact on the progression of fibroblastic sarcoma naturally attract attention." (PMID 34257571, 2021). "The study explored the relationship between HMGB1 and the density of tumor-associated myeloid cells in fibroblastic sarcomas." (PMID 34257571, 2021). "Validation of qPCR showed that the HMGB1 was significantly higher within sarcoma cell lines, such as SW-982, hss-005R, and SW-872, when comparing with the HSF cell line." (PMID 37408763, 2023). "This study detected the expression pattern of HMGB1 in several types of fibroblastic sarcomas including DFSP, MFS and ATFS by immunostaining." (PMID 34257571, 2021). "Therefore, this study aimed to explore the expression pattern and role of HMGB1 in fibroblastic sarcomas, as well as its relationship with tumor-associated myeloid cells, hoping to provide clues as to whether HMGB1 can be a potential therapeutic target for the disease." (PMID 34257571, 2021). "Correlation analysis revealed that the density of CD68, CD163 and CD33 was not only positively correlated with the total score of HMGB1, but also with the cytoplasm-staining score of HMGB1 in fibroblastic sarcomas." (PMID 34257571, 2021). "By immunostaining of 95 tissue microarray cores of fibroblastic sarcomas, HMGB1 was found to be expressed in most tumor tissues." (PMID 34257571, 2021). "Another limitation of this study is that no genetic data were provided on the possible cause of HMGB1 overexpression in fibroblastic sarcomas." (PMID 34257571, 2021). "This study implies that HMGB1 plays an important role in the progression of fibroblastic sarcoma and may serve as a useful prognostic biomarker and a potential therapeutic target for the disease." (PMID 34257571, 2021). "However, no additional studies have focused on the expression and possible role of HMGB1 in fibroblastic sarcomas." (PMID 34257571, 2021). "This means that, in addition to tumor cells, HMGB1 could also be released from vascular endothelial cells to play a certain role in fibroblastic sarcomas." (PMID 34257571, 2021). "The relationship between HMGB1 and tumor-related myeloid cells in fibroblastic sarcoma is unclear." (PMID 34257571, 2021). "Furthermore, obvious cytoplasm-staining of HMGB1 was observed both in tumor cells and vascular endothelial cells and positively correlated with tumor grade in fibroblastic sarcoma." (PMID 34257571, 2021). "Relationship between HMGB1 score and patient characteristics of fibroblastic sarcomas." (PMID 34257571, 2021). "However, the expression pattern and role of HMGB1 in fibroblastic sarcomas is ill defined." (PMID 34257571, 2021). "In order to clarify the expression pattern of HMGB1 in fibroblastic sarcomas, the staining of HMGB1 were detected by IHC assay in 95 TMA cores of fibroblastic sarcomas, which included 54 cases of DFSP, 12 cases of MFS and 29 cases of ATFS." (PMID 34257571, 2021). "In summary, this study implies that HMGB1 released by tumor cells and vascular endothelial cells may modulate the infiltration, polarization and function of TAMs and CD33-positive myeloid cells, thereby contributing to the progression of fibroblastic sarcomas." (PMID 34257571, 2021). "In fibroblastic sarcomas, the total score and the cytoplasm-staining score of HMGB1 were positively correlated with CD68, CD163 and CD33 density, indicating that HMGB1 may act on M2-polarized TAMs and CD33-positive myeloid cells in fibroblastic sarcomas and contribute to disease progression." (PMID 34257571, 2021).
sinusoidal obstruction syndrome (3 papers, 2014 to 2020). "A recent study showed that the increase in serum HMGB-1 is associated with the concurrent decrease in tissue HMGB-1 protein expression of the liver in rat sinusoidal obstruction syndrome." (PMID 25705415, 2014).
spinocerebellar ataxia type 1 (3 papers, 2015 to 2025). Spinocerebellar ataxia type 1 (SCA1) is a subtype of type I autosomal dominant cerebellar ataxia (ADCA type I) characterized by dysarthria, writing difficulties, limb ataxia, and commonly nystagmus and saccadic abnormalities. "Mutant ataxin-1 (Atxn1), which causes spinocerebellar ataxia type 1 (SCA1), binds to and impairs the function of high-mobility group box 1 (HMGB1), a crucial nuclear protein that regulates DNA architectural changes essential for DNA damage repair and transcription." (PMID 25510912, 2015).
synovial sarcoma (3 papers, 2016 to 2025). "In the present study, we analyzed the antitumor activities of OMT in SW982 human synovial sarcoma cells and determine whether high mobility group box protein 1 (HMGB1)-mediated autophagy was associated with its therapeutic effects." (PMID 27897164, 2016). "Therefore, the aim of this study was to investigate the antitumor effects of OMT in human synovial sarcoma and determine whether HMGB1-mediated autophagy was associated with its therapeutic effects." (PMID 27897164, 2016). "Therefore, we believe that combining OMT with an inhibitor of autophagy or HMGB1 may make OMT more effective in the treatment of human synovial sarcoma." (PMID 27897164, 2016). "Based on the results of our study, we report that OMT has potent antitumor activities in SW982 human synovial sarcoma cells and that OMT-induced autophagy promotes drug resistance, which may be mediated by the HMGB1/Akt/mTOR pathway, in SW982 cells." (PMID 27897164, 2016).
toxic epidermal necrolysis (3 papers, 2019 to 2023). Toxic epidermal necrolysis (TEN) is an acute and severe skin disease with clinical and histological features characterized by the destruction and detachment of the skin epithelium and mucous membranes. "Decreased epidermal high‐mobility group box 1 (HMGB1) expression is an early marker of epidermal injury in Stevens–Johnson syndrome/toxic epidermal necrolysis (SJS/TEN)." (PMID 37269158, 2023).
abortion (2 papers, 2021 to 2023). the ending of pregnancy by removing a fetus or embryo before it can survive outside the uterus. "Our previous studies have found that high mobility group box 1 (HMGB1) molecules are highly expressed at the maternal-fetal interface of unexplained recurrent spontaneous abortion (URSA) patients." (PMID 35003098, 2021).
acne (2 papers, 2021 to 2024). An inflammatory process of the sebaceous glands which is characterized by comedones, nodules, papules and/or pustules on the skin. "The results are comparable to previous findings that RF irradiation reduced TNF-α expression in an acne-induced rabbit ear model, but there are few studies showing that RF modulates the expression of HMGB1 and TLRs, which are key molecules in skin inflammation." (PMID 33670841, 2021). "Elevated serum levels of HMGB1 and moesin in severe acne patients suggest that the RAGE axis could contribute to acne pathogenesis." (PMID 39769332, 2024).
acute disseminated encephalomyelitis (2 papers, 2020 to 2021). Acute disseminated encephalomyelitis (ADEM) is a demyelinating disorder of the central nervous system. "We found increased levels of AQP4 in the placenta and fetal membrane in a patient with acute disseminated encephalomyelitis onset in pregnancy as compared to that in a healthy control; this may be due to the activation of the HMGB1/TLR4/Nf-kB/IL-6 pathway." (PMID 35069584, 2021). "This study investigated the possible role of local immune changes and the activation state of the HMGB1/TLR4/Nf-κB/IL-6 pathway at the maternal–fetal interface during pregnancy in the pathogenesis of acute disseminated encephalomyelitis (ADEM)." (PMID 33597947, 2020).
acute lymphoblastic leukemia (2 papers, 2015 to 2025). Leukemia with an acute onset, characterized by the presence of lymphoblasts in the bone marrow and the peripheral blood. "Not only in solid tumors but also in children suffering from acute lymphocytic leukemia (ALL), HMGB1 serum levels were significantly higher in the ALL initial treatment group than in healthy controls and children with complete remission." (PMID 26854151, 2015). "Here, we show that elevated concentrations of HMGB1 have the potential to make such a distinction in a group of patients with acute lymphoblastic leukemia, without apparent clinical infection." (PMID 40868835, 2025). "The novelty of this work is the association of DAMPs (HMGB1) and inflammatory mediators (IL-8, IL-10, IL1-β, and MCP-1) in the development of systemic inflammatory response (SIRS) in pediatric patients with newly diagnosed acute lymphoblastic leukemia (ALL) and no apparent clinical infection." (PMID 40868835, 2025).
alopecia (2 papers, 2019 to 2025). Hair loss usually from the scalp. "The serum HMGB1 level in patients with alopecia universalis is much higher than that in patients with patchy alopecia, alopecia totals and healthy controls and is considered an independent predictor of AA severity." (PMID 40308590, 2025). "Ultimately, our study suggests that HMGB1 may be a novel therapeutic target for hair growth and alopecia treatment." (PMID 31040377, 2019).
anaplastic thyroid cancer (2 papers, 2021 to 2023). "We have shown here that the anaplastic thyroid cancer cell line CAL62 transfers an invasive phenotype to the differentiated cell line BCPAP through the release of EVs that contain miRNAs and proteins such as HMGB1." (PMID 36769076, 2023).
antiphospholipid syndrome (2 papers, 2017 to 2019). A disorder caused by the presence of autoantibodies directed against phospholipids, causing a hypercoaguable state, which may result in blood clots, stroke, heart attack, and in women, significant pregnancy-related complications, including miscarriage and still birth. "Sera from 30 patients with antiphospholipid syndrome (11 primary and 19 secondary APS), 35 subjects with pregnancy morbidity, and 30 healthy women were analysed for HMGB1 and its putative receptor RAGE (sRAGE) by Western blot and for TNF-α by ELISA." (PMID 29410969, 2017).
aortic aneurysm (2 papers, 2016 to 2024). A ruptured aneurysm located in the wall of the proximal portion of the descending aorta proceeding from the arch of the aorta. "Increasing evidence suggests that activation of ERK seems a causal factor for cardiac inflammation by HMGB1, and phosphorylated ERK has been associated with macrophage polarization with aortic aneurysm and inflammatory process." (PMID 27070323, 2016).
arteriosclerosis obliterans (2 papers, 2022 to 2023). Common occlusive arterial disease which is caused by atherosclerosis. "miR-22-3p can regulate human artery vascular smooth muscle cell proliferation and migration by targeting HMGB1, and may be a therapeutic target for the treatment of human arteriosclerosis obliterans." (PMID 37413774, 2023).
asbestosis (2 papers, 2013 to 2017). A lung disorder caused by inhalation of asbestos fibers. "To summarize, serum HMGB1 levels were high in the AE population and particularly high in asbestosis and MM patients." (PMID 28348451, 2017). "Our findings indicated that HMGB1 is a potential biomarker to screen certain subsets of patients with ARDs (asbestosis and MPM) from AE and healthy individuals." (PMID 28348451, 2017). "For clinical diagnosis, these results indicated that serum HMGB1 is a sensitive and specific biomarker to discriminate asbestosis and MM from healthy or AE individuals." (PMID 28348451, 2017). "HMGB1 levels in the asbestosis group (median level: 58.77 ng/mL) were significantly higher than those of the control group, the two AE groups, and the PP group." (PMID 28348451, 2017). "Our findings indicated that serum HMGB1 is a sensitive and specific biomarker for discriminating asbestosis- and MM-affected individuals from healthy or AE individuals." (PMID 28348451, 2017). "In addition, the AUCs for HMGB1 values to distinguish asbestosis from subjects of AE < 10 years, AE ≥ 10 years and healthy controls were 0.74 (95% CI: 0.66–0.83), 0.74 (95% CI: 0.64–0.83), and 0.88 (95% CI: 0.82–0.95), respectively." (PMID 28348451, 2017). "In addition, HMGB1 is also a valuable biomarker in distinguishing patients with asbestosis from healthy control subjects." (PMID 28348451, 2017). "We provide evidence supporting the hypothesis that HMGB1 could be a candidate biomarker in clinical diagnosis for MM and asbestosis." (PMID 28348451, 2017). "From our perspective, HMGB1 may be a suitable blood biomarker to monitor occupational workers and their families who have a history of residential exposure to asbestos, but accurately discriminating MM and asbestosis requires further investigation." (PMID 28348451, 2017). "In the results of univariate regression analysis, dummy variables of PP, AE, asbestosis, and MPM groups showed significant influences on the serum level of HMGB1, with a positive coefficient." (PMID 28348451, 2017). "Our work also found that the protein levels of both MMP2 and MMP9 were not correlated with levels of HMGB1 in sera of patients with asbestosis or MM." (PMID 28348451, 2017). "In addition, the results from the multivariate regression analysis revealed that dummy variables of AE, PP, asbestosis and MPM groups had significantly positive influences on serum HMGB1 levels." (PMID 28348451, 2017). "Interestingly, both MMP2 and MMP9 serum levels were not correlated with HMGB1 in ARDs, including PP, asbestosis and MPM." (PMID 28348451, 2017). "However, the HMGB1 serum level is not useful for discriminating patients with MM from those with asbestosis." (PMID 28348451, 2017). "However, there are no previous statistics of total serum HMGB1 levels to perform a comparison between patients with asbestosis and MM." (PMID 28348451, 2017).
aseptic meningitis (2 papers, 2021 to 2025). Inflammation of the membranes surrounding the brain and spinal cord without a bacterial pathogen. "We determined cerebrospinal fluid (CSF) HMGB1 concentrations and kinetics to evaluate the pathogenesis of BM and compared CSF HMGB1 and IL-6 levels among BM, aseptic meningitis (AM), and controls." (PMID 39849347, 2025).
Atherosclerotic lesion (2 papers, 2017 to 2020). A lesion associated with atherosclerosis, a multifactorial and multipart progressive disease manifested by the focal development within the arterial wall of lesions, that ranges from the development of a fatty streak, plaque progression, and plaque disruption. "Two sources have been proposed to increase HMGB-1 circulating levels, the local HMGB-1 release promoted by damaged immune cells such as monocytes, macrophages, endothelial cells cytokine-triggered, or the secretion from vascular smooth muscle cells (VSMCs) in atherosclerotic lesions." (PMID 28789654, 2017).
autoimmune vasculitis (2 papers, 2016 to 2021). An autoimmune form of vasculitis. "HMGB1 plays an important role in the pathogenic mechanism of autoimmune vasculitis." (PMID 33807604, 2021).
B-cell lymphoma (2 papers, 2022 to 2025). "MPM-1 also induced release of the DAMPs adenosine triphosphate (ATP) and high mobility group box 1 (HMGB1) from Ramos (B-cell lymphoma) and HSC-3 cells, as well as cell surface expression of calreticulin in HSC-3 cells." (PMID 36114339, 2022).
basal cell carcinoma (2 papers, 2013 to 2019). A carcinoma involving the basal cells. "IPA analysis of DEGs revealed that PCP pathway was the top canonical pathways along with HMGB1 signaling, eicosanoid signaling, basal cell carcinoma signaling, CD27 signaling in lymphocytes following exposure to both doses of fipronil with or without LPS." (PMID 30709343, 2019). "In low malignant basal cell carcinoma (BCC), there was diffuse moderate positive expression of HMGB1 in the cancerous epithelial nuclei, and the cytoplasm exhibited focal positive expression." (PMID 23803172, 2013).
borna disease (2 papers, 2013 to 2018). An encephalomyelitis of horses, sheep and cattle caused by borna disease virus. "HMGB1 may also promote virus replications, since the presence of HMGB1 seems important for influenza virus and borna diseases virus replication." (PMID 23435233, 2013).
Brain atrophy (2 papers, 2020 to 2025). Partial or complete wasting (loss) of brain tissue that was once present. "Besides the association with TMEM106B in Subtype B, protective variants near MTUS2 were identified which are in close vicinity to HMGB1, a locus that has been previously implicated in brain atrophy." (PMID 32492070, 2020).
brain hemorrhage (2 papers, 2018 to 2025). "tPA treatment might induce HMGB1 secretion while blocking HMGB1 with HBHP could markedly reduce the risk of thrombolysis-associated brain hemorrhage and mortality through attenuating BBB damage and inflammatory reactions." (PMID 30139371, 2018).
bullous pemphigoid (2 papers, 2025). Bullous pemphigoid (BP) is the most common form of autoimmune bullous dermatosis. "HMGB1 is abundant in the epidermal cytoplasm of pemphigus patients, whereas HMGB1 expression in healthy skin and bullous pemphigoid is almost entirely confined to the nucleus." (PMID 40102153, 2025). "They discovered that serum HMGB1 levels were significantly higher in pemphigus patients than in bullous pemphigoid patients and healthy control populations, and serum HMGB1 levels were significantly higher in pemphigus patients before treatment than after treatment." (PMID 40102153, 2025). "In patients with bullous pemphigoid, neither the serum HMGB1 levels nor the nuclear HMGB1 expression in the skin are significantly different from those in healthy controls." (PMID 40308590, 2025). "Therefore, we suggest that the HMGB1/RAGE interaction may contribute to inflammatory reactions and tissue damage in the pathogenesis of pemphigus but not that of bullous pemphigoid." (PMID 40308590, 2025).
calcific aortic valve disease (2 papers, 2021 to 2022). "Notably, increasing levels of HMGB1 and IL-18 expression have been reported in patients with calcific aortic valve disease." (PMID 36497194, 2022).
cerebral aneurysms (2 papers, 2022). "Recent studies have shown that association between RAG/MR/HMGB1 and ATP1α3 imbalance and inflammatory changes in vulnerable cerebral aneurysms." (PMID 36248807, 2022).
cerebral artery occlusion (2 papers, 2020 to 2022). "To examine the role of platelet HMGB1 in vivo, we used a murine transient middle cerebral artery occlusion (tMCAO) model, in which the right MCA is occluded for 1 hour followed by 23 hours of reperfusion." (PMID 35358095, 2022). "Furthermore, the application of neutralizing monoclonal antibodies against HMGB1 can attenuate the infarct size and severity after middle cerebral artery occlusion in rats." (PMID 33287126, 2020).
cervical tumors (2 papers, 2018 to 2022). "Additionally, HMGB1 expression was significantly higher in colorectal (p < 0.01) and cervical tumors (p < 0.01) than normal tissues according to Oncomine database, which was consistent with our TMA results." (PMID 29844348, 2018).
chondrosarcoma (2 papers, 2016 to 2024). A malignant cartilaginous matrix-producing mesenchymal neoplasm arising from the bone and soft tissue. "The HMGB1/RAGE axis enhances the expression of integrin α5β1 in chondrosarcoma cells and promotes their migration through the PI3K/Akt/c-Jun/AP-1 signaling pathway." (PMID 38529373, 2024).
chronic liver failure (2 papers, 2015 to 2022). Liver failure that develops slowly and gradually for some time, possibly for years, often as the result of cirrhosis, or malnutrition. "HMGB1, RAGE and IL-17 expression is increased in liver of HB patients with acute on chronic liver failure (ACLF) compared to healthy controls." (PMID 26391982, 2015).
Chronic lymphocytic leukemia (2 papers, 2020 to 2024). "Chronic lymphocytic leukemia (CLL) cells exhibit passive release of HMGB1 which are regulated through HMGB1/RAGE/TLR9 signaling and differentiate CD14+ monocytes to nurse-like cells (NLCs)." (PMID 39682695, 2024).